RNU6-1200P (RNA, U6 small nuclear 1200, pseudogene)
Gene: Small nuclear RNA gene on chromosome 3 (117,544,205 to 117,544,311, forward strand). Ensembl gene ENSG00000206889.
Homologues: Orthologues: chimpanzee U6 (99% identical), macaque U6 (91% identical), dog U6 (88% identical), mouse Gm23932 (86% identical), pig U6 (85% identical). Paralogues in human: RNU6-1145P (88% identical), RNU6-1152P (88% identical), RNU6-38P (88% identical), RNU6-589P (88% identical), RNU6-1011P (87% identical), RNU6-15P (87% identical), RNU6-166P (87% identical), RNU6-393P (87% identical), RNU6-41P (87% identical), RNU6-639P (87% identical), RNU6-880P (87% identical), RNU6-10P (86% identical), and 1285 more.